CCL23 (C-C motif chemokine ligand 23)
Description:
Shows chemotactic activity for monocytes, resting T-lymphocytes, and neutrophils, but not for activated lymphocytes. Inhibits proliferation of myeloid progenitor cells in colony formation assays. This protein can bind heparin. Binds CCR1. CCL23(19-99), CCL23(22-99), CCL23(27-99), CCL23(30-99) are more potent chemoattractants than CCL23.
Synonyms: CKB-8; MIP-3; MPIF-1; MIP3; SCYA23; CKb8; CK-BETA-8; Ckb-8-1; hmrp-2a
Tractability: Antibody: its Gene Ontology location is reachable by antibodies, with high confidence; UniProt places it where antibodies can reach, with medium confidence; UniProt predicts a signal peptide or a membrane-spanning region.
Gene: Protein-coding gene on chromosome 17 (36,013,056 to 36,017,972, reverse strand). Ensembl gene ENSG00000274736.
Subcellular location: Secreted
Pathways (Reactome):
Signal Transduction: Formyl peptide receptors bind formyl peptides and many other ligands; G alpha (i) signalling events; G alpha (q) signalling events
Gene Ontology:
Molecular function: CCR1 chemokine receptor binding; chemokine activity; protein binding; CCR chemokine receptor binding
Biological process: antimicrobial humoral immune response mediated by antimicrobial peptide; cell chemotaxis; cell-cell signaling; chemokine-mediated signaling pathway; chemotaxis; G protein-coupled receptor signaling pathway; immune response; inflammatory response; intracellular calcium ion homeostasis; monocyte chemotaxis; negative regulation of cell population proliferation; positive regulation of cell migration; signal transduction
Cellular component: extracellular region
Genetic constraint (gnomAD): Loss-of-function variants: 8 observed, 10.18 expected, observed/expected ratio (o/e) 0.79, 90% interval 0.46 to 1.41. The upper end of that interval is the gene's LOEUF score, 1.41, which puts it in group 5 of 6, group 1 being the genes least tolerant of losing a copy. Missense variants: 145 observed, 153.47 expected, observed/expected ratio (o/e) 0.94, 90% interval 0.82 to 1.08. Synonymous variants: 49 observed, 54.51 expected, observed/expected ratio (o/e) 0.9, 90% interval 0.71 to 1.14.
Homologues: Orthologues: chimpanzee CCL23 (99% identical), dog CCL23 (39% identical), mouse Ccl9 (36% identical), mouse Ccl6 (33% identical), rat Ccl9 (33% identical), zebrafish ccl35.1 (20% identical), zebrafish ccl35.2 (20% identical). Paralogues in human: CCL15 (59% identical), CCL3 (33% identical), CCL3L3 (33% identical), CCL14 (30% identical), CCL7 (29% identical), CCL4 (28% identical), CCL18 (28% identical), CCL11 (27% identical), CCL4L2 (26% identical), CCL2 (26% identical), CCL5 (26% identical), CCL8 (26% identical), and 14 more.
Diseases named in the same sentence as CCL23 in open-access papers:
CCL23 is named in the same sentence as 97 diseases in open-access papers, as found by Europe PMC text mining. Sharing a sentence is not in itself a finding about the gene and the disease. The quoted sentences say what the papers report.
COVID-19 (20 papers, 2020 to 2025). A disease caused by infection with severe acute respiratory syndrome coronavirus 2. "This is supported by our data showing that a high level of CCL23 is associated with poor outcomes in patients with COVID-19." (PMID 34789851, 2021). "Furthermore, CCL23 and MCPs have been connected to the severity of the clinical presentation of COVID-19 while being linked to the emergence of chronic neurodegeneration under other circumstances." (PMID 34944606, 2021). "A novel subset of pro-inflammatory neutrophils expressing a high level of dual endothelin-1 and VEGF signal peptide-activated receptor (DEspR) at the cell surface was found to be associated with elevated circulating CCL23, increased NETosis, and critical-severity COVID-19 illness." (PMID 34789851, 2021). "An association was seen between the number of DEspRhigh neutrophils, NETosing neutrophils, the blood plasma level of CCL23, and critical illness in COVID-19." (PMID 34789851, 2021). "We found that several neurodegeneration markers (YKL40, NCAM-1, CCL23) were elevated in survivors of COVID-19 in a sustained fashion." (PMID 34944606, 2021). "Both DEspRhigh neutrophils and CCL23 were significantly increased in critically ill patients with COVID-19." (PMID 34789851, 2021). "The level of CCL23 was significantly increased in patients with COVID-19 compared to control subjects." (PMID 34789851, 2021). "In contrast, pro-inflammatory cytokines and chemokines, including CCL14, CCL23, IL7, IL16 and IL18, were preferentially expressed in men, underlying the higher susceptibility of men developing cytokine release syndrome in COVID-19." (PMID 32974111, 2020). "Importantly, IL-17C, MMP-10, FGF-23 and CCL23 are upregulated only in asymptomatic participants early after infection, which strongly suggests their role in the control of COVID-19 clinical signs." (PMID 35479098, 2022). "Our study demonstrated elevated levels of circulating CCL23 in patients with COVID-19." (PMID 34789851, 2021). "In moderate COVID-19, we observed differential outflow of fewer inflammatory cytokines, including CCL5 and CCL23." (PMID 39187683, 2024). "CCL23, among the other seven proteins (IL-17C, MMP-10, FGF-19, FGF-21, FGF-23, and CXCL5), was higher in asymptomatic COVID-19 patients than in patients with symptoms." (PMID 37834869, 2023). "COVID-19 patients showed significant correlations (all p < 0.01) of hs-CRP with IL8 (r = 0.421), MCP3 (r = 0.660), CXCL10 (r = 0.391), CCL23 (r = 0.555), and IL6 (r = 0.687)." (PMID 37832397, 2023). "The most striking feature of liver failure was the elevation of CCL23, FGF2, and KRLD1 and depression of KIR3DL1 at admission, while Gal-1 and DCN were decreased later during the history of COVID-19." (PMID 34177897, 2021). "Our analysis revealed a positive correlation between the number of DEspRhigh neutrophils, but not total neutrophils, and the level of circulating CCL23 in patients with COVID-19." (PMID 34789851, 2021). "During the second phase of COVID-19, pneumonia patients exhibit features of macrophage activation syndrome (MAS) in which macrophages play a major pro-inflammatory role by releasing pro-inflammatory cytokines such as IL-6, IL-8 and CCL23." (PMID 33446817, 2021). "Severe COVID-19 in controls, but not SOT recipients, was associated with a marked increase in several canonical proinflammatory serum cytokines and chemokines (e.g., IL-6, CCL23, and CXCL8)." (PMID 39794319, 2025). "When analyzing the COVID-19 patients age-related (cut-off median = 69 years) by dividing them into an older and younger subgroup, it has been shown that hs-CRP correlated significantly with MCP3 (r = 0.577), CCL23 (r = 0.542) and IL6 (r = 0.722, all p < 0.01) in younger COVID-19 patients." (PMID 37832397, 2023). "However, in older COVID-19 patients more and stronger correlations could be detected with hs-CRP (all p < 0.01): IL8 (r = 0.548), MCP3 (r = 0.720), CXCL10 (r = 0.460), CCL23 (r = 0.577) and IL6 (r = 0.706)." (PMID 37832397, 2023).
COVID-19 (continued). "To explore whether the leucocyte response is limited by COVID-19, we stimulated cells with LPS or PMA/Ion, and a clear proinflammatory response with cytokines such as TNF-α, CCL3, CCL4, IL-17a, CCL23 and CXCL8 was detected in the supernatant, indicating that leucocytes are not anergic." (PMID 35901034, 2022). "The sustained elevation of YKL40, NCAM-1, and CCL23 may represent an ongoing pathological process in the survivors of COVID-19 as the levels did not decline below those recorded at admission." (PMID 34944606, 2021). "A positive correlation was found between the number of DEspRhigh neutrophils, but not the total number of neutrophils, and the level of CCL23, indicating there may be a direct relationship between these two factors in the development of critical COVID-19." (PMID 34789851, 2021).
ovarian carcinoma (11 papers, 2017 to 2025). A malignant neoplasm originating from the surface ovarian epithelium. "Our findings show that elevated CCL23 concentrations in ascitic fluid are associated with a reduced overall survival in patients with advanced epithelial ovarian cancer." (PMID 41463176, 2025). "However, the extent to which ascites-derived CCL23 concentrations associate with changes in pro- and anti-inflammatory cytokines and overall patient survival in ovarian cancer patients remains unknown." (PMID 41463176, 2025). "In ovarian cancer, CCL23, produced by macrophages, was involved in the formation of an immunosuppressive TIME in ovarian cancer by inducing the depletion of T cell phenotypes." (PMID 40149008, 2025). "We evaluated the composition of ovarian cancer ascites for 95 unique markers in patient samples containing high, intermediate, and low CCL23 levels." (PMID 41463176, 2025). "The current report builds on prior findings which demonstrated that CCL23 facilitates ovarian cancer metastasis to the omentum and contributes to TME formation." (PMID 41463176, 2025). "The study also observed a prominent inverse association between CCL23 and CXCL10 levels in ovarian cancer patient samples that correlated with patient survival." (PMID 41463176, 2025). "This study explores how a specific immune signal, CCL23, found in the ascites of ovarian cancer patients, affects the tumor microenvironment and patient survival." (PMID 41463176, 2025). "For example, previous studies in our laboratory highlight the role of macrophage-secreted CCL23 promotes the migration and colonization of ovarian cancer cells to the omentum via the CCR1 signaling axis." (PMID 41463176, 2025). "We measured ascites-derived CCL23 concentrations and changes in pro-inflammatory cytokines from ovarian cancer patients’ samples and further evaluated survival from patient outcome data." (PMID 41463176, 2025). "Prior work from our laboratory has also found that CCL23 signaling is necessary and sufficient to promote ovarian cancer cell migration as well as metastasis from solid ovarian cancer tumors in the homologous murine pathway." (PMID 41463176, 2025). "In ovarian cancer, macrophage-derived CCL23 was shown to contribute to an immune-suppressive tumor microenvironment by inducing an exhausted T-cell phenotype." (PMID 36505756, 2022). "Chemokine-ligand-23 (CCL23) secreted by macrophages induces ovarian cancer cell migration via chemokine receptor 1 (CCR1)." (PMID 36359346, 2022). "One of the studies revealed that CCL23 was necessary and sufficient to promote the migration of ovarian cancer." (PMID 35001801, 2022). "Recently, numerous studies have indicated that CCL23 is essential for the inflammation of several human diseases, including ovarian cancer, chronic rhinosinusitis, chronic kidney disease, eosinophilic airway inflammation, and ischemic stroke." (PMID 36498453, 2022). "Neutralization of CCL6 and CCL23 in these complex environments with a large variety of other chemokine ligands completely abrogated the migration of ovarian cancer cells." (PMID 32963283, 2020). "CCL6 and the human homolog CCL23 were both necessary and sufficient to promote ovarian cancer migration by activating ERK1/2 and PI3K pathways." (PMID 32963283, 2020). "We demonstrate that macrophage secreted CCL6 or CCL23 promotes colonization of ovarian cancer cells to omental milky spots." (PMID 32963283, 2020). "We hypothesize that human ovarian cancer ascites act as a reservoir of CCL23, and that high CCL23 concentrations promote an immunosuppressive phenotype and adverse patient outcomes." (PMID 41463176, 2025). "Overall, high levels of CCL23 were indicative of reduced patient outcomes, suggesting that CCL23 could be a useful biomarker for assessing immune responsiveness in ovarian cancer patients." (PMID 41463176, 2025). "CCL23 expression also correlated with the presence of macrophages in ovarian cancer tissues." (PMID 36359346, 2022).
ovarian carcinoma (continued). "Therefore, we investigated the ability of CCL6 and CCL23 to enhance migration of mouse and human ovarian cancer cell lines." (PMID 32963283, 2020). "Interestingly, the CCL23 was reported to be sufficient to promote ovarian cancer migration." (PMID 35001801, 2022). "CCL23 could promote ovarian cancer migration by activating the ERK1/2 and PI3K pathways." (PMID 35665772, 2022). "This study suggests that targeting CCR1 or CCL23 in ovarian cancer may be a therapeutic strategy." (PMID 32963283, 2020). "CCL23 mediated signaling via the CC chemokine receptor 1 (CCR1) promotes TME formation, tumor cell migration, and colonization of ovarian cancer cells to the omentum." (PMID 41463176, 2025). "Such an understanding of the crosstalk between CCL23, STAT3, and CXCL10 provides new insights into future therapeutic targets and improving the responsiveness of ovarian cancers to current immune-oncology therapies." (PMID 41463176, 2025). "CCL23 is the natural ligand for the cognate receptor, CCR1, which promotes tumor-supportive processes such as the recruitment of myeloid cells, endothelial cell migration, angiogenesis, and T-cell exhaustion in ovarian cancer." (PMID 41463176, 2025). "Despite these established roles in metastasis and immune exhaustion, the specific contribution of ascites-derived CCL23 to immune modulation in human ovarian cancer has not been characterized." (PMID 41463176, 2025). "CCL23-mediated signaling increases pro-inflammatory cytokine expression in the TME, yet it was unclear whether ovarian cancer ascites also harbored differences in other pro- and anti-inflammatory cytokines." (PMID 41463176, 2025). "A role for CCR1 in cancer metastasis has been suggested in other studies, but not in the context of ovarian cancer or mediated by omental macrophage-derived CCL6/CCL23." (PMID 32963283, 2020). "Recently, CCL23 was demonstrated to promote the migration of human ovarian cancer cells in vitro by activating ERK1/2 and PI3K pathways and was hypothesized to be an important mediator of metastatic cell colonization in the omentum in advanced ovarian cancer patients." (PMID 37185750, 2023).
breast carcinoma (10 papers, 2020 to 2026). "Proteins involved in chemotaxis and inflammation, including CCL3, CCL4, CXCL11, and CCL23, were only found to be associated with long-term breast cancer risk after five years, suggesting the long-term effect of inflammation on breast cancer risk." (PMID 40665092, 2025). "Furthermore, a previous study found that a risk model composed of PTGDR, PNOC and CCL23 was helpful in predicting the prognosis of HER2-positive breast cancer, and that patients with low risk scores may benefit from immunotherapy." (PMID 41383978, 2026). "With respect to the seven measured chemokines, CXCL5 and CCL23 were substantially decreased in the group of breast cancer patients, while those of CX3CL1 (fractalkine) and CCL5, were significantly elevated." (PMID 35677046, 2022). "According to the ‘The Human Protein Atlas’, increased expression of CCL23 is beneficial to the prognosis of liver, prostate and breast cancers, while it has the opposite effect on that of intestine, endometrium cancers and glioma." (PMID 35001801, 2022). "In breast cancer patients, levels of CCL23 and CCR1 expression correlated with metastasis and decreased survival; however, HER2-positive breast cancer cases corresponded with low levels of CCL23/CCR1 expression and better prognosis." (PMID 37185750, 2023). "The identified CCL proteins have various carcinogenetic properties, such as the increase in breast cancer cell proliferation, chemoresistance development and T-cell and NK-cell regulation (CCL8), stimulation of angiogenesis and cancer cell proliferation (CCL23) and control of cell migration (CCL28)." (PMID 38594742, 2024). "Based on their functions in biology and carcinogenesis, the current results imply that serum CCL8, CCL23 and CCL28 could also be drivers of aggressive breast cancer behavior in situ." (PMID 38594742, 2024).
Alzheimer disease (8 papers, 2021 to 2025). A progressive, neurodegenerative disease characterized by loss of function and death of nerve cells in several areas of the brain leading to loss of cognitive function such as memory and language. "It is also worth noting that the CCL6 ortholog gene product in human, CCL23, has been reported as a diagnostic biomarker in the serum or cerebrospinal fluid of patients with Alzheimer’s disease and ischemic stroke." (PMID 35974004, 2022). "Elevated CCL23 levels are reported in various inflammatory diseases and is, in addition, associated with progression from mild cognitive impairment to Alzheimer’s disease (AD)." (PMID 34863228, 2021). "Similarly to CCL21, CCL23 was associated with progression from mild cognitive impairment (MCI) to Alzheimer’s disease (AD)." (PMID 40149697, 2025). "Additionally, the involvement of CCL23 in neuroinflammation associated with neurodegenerative diseases such as Alzheimer’s Disease (AD) and Parkinson’s Disease (PD) also provides corresponding evidence." (PMID 39544374, 2024).
Stroke (7 papers, 2021 to 2025). Sudden impairment of blood flow to a part of the brain due to occlusion or rupture of an artery to the brain. "Elevations in CCL23, a cytokine involved in the recruitment of leukocytes to nervous system compartments and linked to vascular injury-related stroke, could suggest an influx of peripheral leukocytes into the brain." (PMID 34944606, 2021). "These include PD-L1 and TRAIL, two pro-inflammatory proteins whose downregulation has beneficial effects in models of stroke and CCL23, a chemokine that induces further expression of inflammatory proteins in a feed-forward mechanism." (PMID 40703679, 2025). "In non-COVID-19 stroke patients, elevated levels of CCL23 are associated with the severity of brain damage and have been suggested as possible biomarkers for assessing stroke prognosis." (PMID 37834869, 2023).
liver cancer (6 papers, 2021 to 2025). An epithelial or non-epithelial malignant neoplasm that arises from the liver. "We extracted the mRNA expression profile from a TCGA data set (TCGA Liver Cancer) for normal tissues and primary tumors to elucidate the potential role of CCL23 in association with the immunobiology of hepatocellular carcinoma." (PMID 34671553, 2021). "CCL23 was a risk factor in liver cancer and a protective factor in biliary tract cancer." (PMID 38075694, 2023). "The results of MR analysis showed that significant causal association between CCL15 [OR (95%CI), 0.848 (0.730–0.985), p = 0.03] and CCL23 [OR (95%CI), 1.306 (1.020–1.673), p = 0.03] and malignant neoplasm of liver (finn-b-C3_LIVER_INTRAHEPATIC_BILE_DUCTS)." (PMID 38075694, 2023). "Cochrane’s Q test did not provide evidence of heterogeneity between CCL15 (p = 0.698) and CCL23 (p = 0.978) and liver cancer." (PMID 38075694, 2023). "The multivariate Cox regression analysis revealed a significantly lower expression of CCL23 in liver cancer tissues compared to adjacent normal." (PMID 34671553, 2021). "We further selected mRNA (RNA-seq) liver cancer data sets from Kaplan Meier (KM) Plotter for the pan-cancer and examined the correlation between CCL23 mRNA and the survival probability." (PMID 34671553, 2021). "Analysis of the data set from the cohort TCGA Liver Cancer showed a significantly lower (p = 0.0001) expression of the CCL23 transcript in HCC compared to normal liver tissue." (PMID 34671553, 2021). "However, a liver cancer study showed that CCL23 could suppress tumor progression by promoting the immune infiltration of CD8 T cells." (PMID 35665772, 2022). "CCL23 has been found to be underexpressed in hepatoma cells, and this could lead to CCL23 deletion and reduced CCL23 inhibition via the ESR1/CCL23/CCR1/AKT regulatory axis in liver cancer progression." (PMID 36425563, 2022).